FGF23 (fibroblast growth factor 23)
Diseases named in the same sentence as FGF23 in open-access papers (continued):
Sharing a sentence is not in itself a finding about the gene and the disease.
cardiac hypertrophy (continued). "Furthermore, FGF-23 levels, even if within the normal range, show a correlation with left ventricular mass, hypertrophy and geometry in a community-based cohort." (PMID 34222283, 2021). "Besides the role in cardiac hypertrophy, current findings indicate that FGF23 is involved in the pathophysiological signaling pathways that result in the development of cardiac fibrosis." (PMID 34065339, 2021). "In particular, FGF-23 has been linked to a greater risk of concentric hypertrophy, which is apparently a compensated cardiac hypertrophy that results in increased wall thickness without ventricular dilation." (PMID 33767635, 2021). "Mechanistically, it was shown that FGF23 directly induces hypertrophic growth of cardiac myocytes in vitro and cardiac hypertrophy in vivo that was abolished by inhibition of phospholipase Cγ (PLCγ) or calcineurin, but not by the use of MAP kinase, PI3 kinase or Akt inhibitors." (PMID 34422725, 2021). "A connection of FGF23, cardiac hypertrophy and the local RAAS in the heart is also discussed." (PMID 34422725, 2021). "Besides the connection to Ca2+ signaling and RAAS in developing myocardial hypertrophy, studies also pointed out the importance of Wnt signaling and the cross-talk to FGF23 in this pathology." (PMID 34065339, 2021). "Rather increased phosphate level as well as more pronounced cardiac hypertrophy were observed compared to uremic controls leading the authors to the conclusion that elevated FGF23 level in CKD may have a protective role to maintain cardiac homeostasis." (PMID 34422725, 2021). "Paricalcitol mediated downregulation of RAAS and NFAT, respectively, together with diminished FGF23 level could thus attenuate cardiac hypertrophy." (PMID 34422725, 2021). "Thus, leading to the conclusion that beside FGFR4/PLCγ/calcineurin signaling pathway, FGF23 promotes cardiac hypertrophy and fibrosis via activation of intra-cardiac RAAS." (PMID 34422725, 2021). "It is reported that FGF23 induces cardiac hypertrophy by Klotho-independent binding to FGFR4." (PMID 34765890, 2021). "It has been revealed that kidney disease-induced “unintended” systemic inhibition of Wnt activity is associated with severe consequences in the skeleton and vasculature, such as decreased bone formation rates, elevated FGF23 secretion, vascular calcification, and promotion of cardiac hypertrophy." (PMID 34208727, 2021). "Similar to the FGF23-mediated cardiac hypertrophy via induction of calcineurin/NFAT pathway, the activation of RAAS by FGF23 in NRVM causes cardiomyocyte hypertrophy, which can be blocked by the angiotensin receptor blocker losartan, and the mineralocorticoid receptor antagonist spironolactone." (PMID 33416083, 2021). "In addition, overexpression of FGF23 in the myocardium also induced cardiac hypertrophy, increased myocardial cell area and upregulated the expression of hypertrophic related genes." (PMID 33460402, 2021). "A positive correlation between FGF23 and cardiac hypertrophy exists in a Klotho-deficient state, but not in a Klotho-repleted state." (PMID 32150864, 2020). "FGF23 could be a possible target of treatments intended to prevent fibrosis following myocardial hypertrophy." (PMID 32315372, 2020). "Interestingly, an additive effect between FGF23 and HP was observed in inducing cardiac hypertrophy and energy metabolism remodeling." (PMID 32938919, 2020). "This FGFR4-mediated effect may play a key role in cardiac hypertrophy through FGFR4 during highly elevated FGF23 in CKD." (PMID 32982979, 2020). "This supports the hypothesis that phosphate promotes LVH by stimulating FGF23, which is known to induce cardiac hypertrophy via FGFR4." (PMID 31698866, 2019). "In this trial, the level of FGF23 will be modified by either the calcimimetic etelcalcetide (ETL) or alfacalcidol (ALFA) at a PTH clamp, and therefore will be able to test the causality of FGF23 reduction on cardiac hypertrophy and fibrosis." (PMID 31651370, 2019).
cardiac hypertrophy (continued). "Additionally, they showed that the administration of chlorothiazide completely prevents FGF23-induced volume expansion and heart hypertrophy." (PMID 31651370, 2019). "Animal models with elevated serum FGF23 levels, induced by CKD, genetic deletion of klotho, injection of recombinant FGF23 protein, or a high phosphate diet, develop cardiac hypertrophy, which can be blocked by administration of specific inhibitors for FGFR4 or calcineurin." (PMID 29770125, 2018). "FGF-23 is the most important P-regulating hormone and increases P excretion when the serum phosphate level is too high, but FGF-23 also decreases the vitamin D levels, promotes ventricular hypertrophy, accelerates the deterioration of renal function and increases cardiovascular mortality." (PMID 30401006, 2018). "The fact that blood pressure is elevated in Hyp mice while low in kl/kl mice further supported the hypothesis that FGF23-mediated cardiac hypertrophy might be blood pressure independent." (PMID 29977226, 2018). "Interestingly, high phosphate diet also stimulated FGF23-induced cardiac hypertrophy and fibrosis in wild-type C57BL/6J mice that was reversible after switching to regular diet." (PMID 30200452, 2018). "While normalization of serum FGF23 and phosphate levels by dietary phosphate restriction and blood pressure with antihypertensive drugs did not reverse cardiac hypertrophy in Klotho-deficient CKD mice." (PMID 30200452, 2018). "Intravenous delivery of a transgene encoding soluble Klotho ameliorated cardiac hypertrophy in Klotho-deficient CKD mice without changes in serum FGF23 and phosphate levels." (PMID 30200452, 2018). "The present results suggest that the differences in serum calcium and phosphate levels between the two mouse models may contribute to the effects on cardiac hypertrophy and fibrosis at high FGF23 levels." (PMID 29977226, 2018). "Whether cardiac FGF23 alone is sufficient to induce spontaneous cardiac hypertrophy and fibrosis and whether high cardiac synthesis of FGF23 always leads to the progression of HF must be investigated in further studies." (PMID 29892269, 2018). "Instead, the cardiac myocyte-specific deletion of the FGF23 receptor, i.e., FGFR4, followed by the elevation of circulating FGF23 should help to determine whether direct cardiac actions of FGF23/FGFR4 contribute to cardiac hypertrophy." (PMID 29770125, 2018). "Taken together, our data suggest that the well-established cardiac FGF23/FGFR4 signaling involved in the development of pathologic cardiac hypertrophy with the parallel appearance of cardiac fibrosis is induced in kl/kl mice with high FGF23 levels and klotho deficiency." (PMID 29977226, 2018). "Neither deletion of Fgf23 protected against pressure overload-induced cardiac hypertrophy and fibrosis, nor klotho deficiency exacerbated TAC-induced pathological hypertrophic phenotype in mice." (PMID 29892269, 2018). "Therefore, the role of FGF23 and Klotho in the pathophysiology of heart hypertrophy is still unclear." (PMID 28900153, 2017). "Faul and colleagues have shown in a mouse model that FGF23 application results in myocardial hypertrophy, a finding that might be driven by FGF23 binding at the FGF receptor 4 (FGFR4) on myocardial tissue." (PMID 29073196, 2017). "We found that neither Fgf23 nor Klotho deficiency modulates cardiac hypertrophy induced by pressure overload." (PMID 28900153, 2017). "Recombinant klotho ameliorated CKD-associated cardiac hypertrophy without significantly altering serum phosphate and/or FGF23 levels." (PMID 29250031, 2017). "To test the hypothesis that Fgf23 and Klotho play an essential role in the development of cardiac hypertrophy induced by increased afterload, we induced TAC in wild-type (WT), VDRΔ/Δ, Fgf23−/−/VDRΔ/Δ, and Klotho−/−/VDRΔ/Δ mice." (PMID 28900153, 2017).
cardiac hypertrophy (continued). "In contrast to wild-type and VDRΔ/Δ mutant mice, rFGF23 treatment of 3-month-old Kl−/−/VDRΔ/Δ double mutant mice did not result in renal Na+ retention and heart hypertrophy, showing that the effects of FGF23 on Na+ homeostasis and heart hypertrophy are Klotho dependent, but VDR independent." (PMID 24797667, 2014). "The NCC inhibitor chlorothiazide abrogates FGF23-induced volume expansion and heart hypertrophy." (PMID 24797667, 2014). "FGF23 also induces cardiac hypertrophy by activating calcineurin/NFAT signaling." (PMID 24046748, 2013). "Moreover, such an elevation of cardiomyocyte-derived circulating FGF23 resulting from cardiac hypertrophy may not only alter phosphate homeostasis but also increase the overall metabolic burden, as well as hypertension and hemodynamic abnormalities." (PMID 41038963, 2025). "Though these studies have focused on pathologic hypertrophy, the significant elevation of FGF23 over the course of exercise training and pregnancy suggests that FGF23/FGFR4 signaling could play a role in physiologic cardiac hypertrophy as well, which is supported by our study." (PMID 39452290, 2024). "In pathological scenarios of massive FGF23 elevations, such as CKD, FGF23 can bind and activate FGFR4 in a klotho-independent manner, thereby stimulating phospholipase Cγ (PLCγ)/calcineurin signaling and causing pathologic alterations, such as cardiac hypertrophy." (PMID 38791164, 2024). "Interestingly, FGF23 elevations induced by a high-phosphate diet in the absence of CKD seem to cause cardiac hypertrophy that is reversible." (PMID 39452290, 2024). "Thus, while FGF23 may be an important mediator of cardiac hypertrophy in CKD, FGF21 may have an especially important role in the induction of concentric hypertrophy in diabetic cardiomyopathy." (PMID 35513431, 2022). "In addition, FGF23 increases renal sodium reabsorption by upregulating the Na+:Cl− cotransporter in the distal tubules via a Klotho-dependent pathway, leading to volume expansion, hypertension, and cardiac hypertrophy." (PMID 34765890, 2021). "While it does not directly contribute to vascular calcification, FGF-23 causes cardiac hypertrophy." (PMID 34222283, 2021). "Interestingly, non-CKD and non-hypertensive models with FGF23 excess such as Hyp or Phex-C733R mice, both models with mutation in the Phex gene and consequently excessively high FGF23 levels, do not display cardiac hypertrophy." (PMID 33416083, 2021). "In the absence of intestinally derived FGF15, VSG leads to an even greater increase in hydrophobic bile acids which we speculate leads to anemia of chronic disease and increased EPO and FGF23 levels that likely contribute to great loss of bone mass, BMAT, muscle mass, and cardiac hypertrophy." (PMID 34362888, 2021). "The increase of FGFR4 expression in the heart of the CRS mice maybe attributable to the compensatory myocardial hypertrophy induced by MI and the upregulation of its ligand FGF23, and the similar phenomenon has been reported from both experimental and clinical investigations." (PMID 33460402, 2021). "These lines of evidence suggest that FGF23-induced cardiac hypertrophy is reversible in vitro and in vivo, following the removal of hypertrophic stimulus, and indicate that pharmacological interference with cardiac FGF23/FGFR4 signaling might provide protection from CKD- and age-related LVH." (PMID 33000285, 2021). "Interestingly, recent studies demonstrated an opposite directional relationship—injured cardiomyocyte could produce substantial amounts of FGF23 after myocardial infarction or during cardiac hypertrophy." (PMID 34765890, 2021). "PTH might indirectly induce myocardial hypertrophy by increasing FGF-23 synthesis." (PMID 32192220, 2020). "Furthermore, an experimental study has shown a direct effect of FGF-23 on myocardial hypertrophy." (PMID 32192220, 2020).
cardiac hypertrophy (continued). "Our study indicates that hypertrophic stimuli may not be sufficient to induce FGF23 in the heart, although a number of previous studies have demonstrated that FGF23 is associated with myocardial hypertrophy." (PMID 32315372, 2020). "FGF23 could be a possible target to prevent fibrosis following myocardial hypertrophy." (PMID 32315372, 2020). "Hence, the observed cardiac hypertrophy might be triggered by phosphate-induced elevations of serum FGF23 as well." (PMID 31698866, 2019). "Here, we investigated whether FGF23-mediated activation of endogenous cardiac RAAS contributes to cardiac hypertrophy and fibrosis by using the well-established 5/6 nephrectomy (5/6Nx) rat model of experimental uremia followed by in vitro analyses in NRVM and NRCF." (PMID 31540546, 2019). "Particularly, it provides evidence that CKD-associated cardiac hypertrophy correlates with reduced eGFR and soluble Klotho and Vitamin D levels, and is indicative of a generalized pro-inflammatory status, as evidenced by increased levels of IL-6, ACR, PTH, P and FGF23." (PMID 30934737, 2019). "Furthermore, to determine whether circulating FGF23 might contribute to physiologic cardiac hypertrophy requires studies in animals with genetic modifications of the FGF23/FGFR4 signaling pathway in the heart." (PMID 29770125, 2018). "However, alternative mechanisms include direct effects of phosphate on endothelial function, and effects mediated by regulators of phosphate homoeostasis, including fibroblast growth factor 23 (FGF-23), a phosphaturic hormone implicated in cardiac hypertrophy, another common feature of CKD." (PMID 27448672, 2017). "Furthermore, we study whether lowering FGF23 concentrations can reduce established cardiac hypertrophy, which has been induced by FGF23 elevation in vitro and in vivo." (PMID 28512310, 2017). "However, chronically elevated FGF23 levels may become maladaptive to directly stimulate cardiomyocyte growth and induce cardiac hypertrophy in patients with CKD." (PMID 29250031, 2017). "Indeed, there is a close relationship between hypervolemia, pulse pressure, hypertrophy of left ventricle and fibroblast growth factor-23 (FGF-23) that are factors of morbidity and cardiovascular mortality in HD by contributing to atherosclerosis and vascular calcifications." (PMID 27871253, 2016). "Therefore, excessive FGF23 signaling may induce cardiac hypertrophy by salt and volume retention, leading to hypertension and increased afterload." (PMID 25858796, 2015). "However, long‐term exposure to FGF23 may lead to the disturbance of calcium circulation, which in turn activates the transcriptional remodelling mechanism, resulting in long‐term functional impairment and ultimately leading to heart hypertrophy." (PMID 40126903, 2025). "Finally, transverse aortic constriction (TAC) was performed in adult wild-type mice, double Fgf23/VDR (fibroblast growth factor-23/vitamin D receptor) mutants, and VDR-deficient mice to investigate bone changes in an HF model caused by afterload-induced cardiac hypertrophy, 4 and 6 weeks after TAC." (PMID 41515999, 2025). "However, whether FGF23 can induce physiologic cardiac hypertrophy is currently unknown." (PMID 39452290, 2024). "Rhein significantly inhibits the expression of FGF23 through the activation of AMPK, inhibits Ang II-induced cardiac hypertrophy and fibrosis through the AMPK/FGF23 axis, and improves cardiac systolic dysfunction." (PMID 39770507, 2024). "This review describes the FGF23 role in cardiac hypertrophy and anemia in the setting of CKD and discusses the best therapeutical approach for lowering FGF23 levels." (PMID 36831276, 2023). "FGF23 activates FGFR4/phospholipase Cγ/calcineurin/nuclear factor of activated T-cells (NFAT) signaling in cardiomyocytes and induces cardiac hypertrophy in rodents." (PMID 36909314, 2023).
cardiac hypertrophy (continued). "Thus, through the pathological signaling processes involving cardiac myocytes and immune cells, angiotensin II, and aldosterone, as active RAAS components, FGF23 may induce vascular and myocardial fibrosis and cardiac hypertrophy apart from the effect on elevated blood pressure." (PMID 36831276, 2023). "FGF23 activated the PLCγ phosphorylation and the calcineurin/NFAT signaling pathway, finally upregulating the expression of cardiac hypertrophy-related genes." (PMID 35801203, 2022). "Hence, FGF23 alone may not be sufficient to cause cardiac hypertrophy, but a combination of factors and perhaps a specific microenvironment induced by CKD is needed." (PMID 33416083, 2021). "In the same regard, cardiac hypertrophy due to elevated phosphate and Fgf23 was reversed by lowering dietary phosphate intake in vivo, supporting the hypothesis that cooperative interaction of FGF23 and high phosphate needs to be present for the development of LVH in CKD and non-CKD." (PMID 34778257, 2021). "Cardiac hypertrophy and fibrosis are common comorbidities in CKD patients and it is well-established that FGF23 directly promotes LVH via calcineurin/NFAT signaling activation in uremia." (PMID 31540546, 2019). "Therefore, one could speculate that mice did not develop cardiac hypertrophy, since they lack pathologic stimuli released by activated renal fibroblasts and/or associated with kidney fibrosis that act in synergy with FGF23 to harm the heart." (PMID 29770125, 2018). "Fibroblast growth factor 23 (FGF-23) is a phosphorus-regulating hormone and plays a role in the pathogenesis of myocardial hypertrophy." (PMID 30462803, 2018). "To shed more light on the possible pathophysiological role of FGF23 in the development of hypertrophy and heart failure we employed TAC, a pressure overload-induced hypertrophy model." (PMID 28900153, 2017). "In ESRD, high serum phosphate levels, high fibroblast growth factor 23 (FGF23) levels and low serum Klotho levels are considered to play a role in cardiac hypertrophy and cardiac fibrosis." (PMID 27189482, 2016). "Furthermore, in the logistic regression model, the significant association between FGF23 and cardiac hypertrophy was retained after adjusting for not only serum levels of calcium and inorganic phosphate but also use of diuretic drugs, which have been shown to potently alter serum FGF23." (PMID 27400031, 2016). "This suggests that klotho deficiency is a primary contributor to cardiac hypertrophy in CKD, independent of FGF23 and phosphate." (PMID 40559238, 2025). "CKD mice lacking klotho exhibited more severe cardiac hypertrophy after controlling for serum phosphate and FGF23 levels." (PMID 40559238, 2025). "FGF23 activates fibroblast growth factor receptor 4 (FGFR4) phospholipase Cγ/calcineurin/nuclear factor of activated T cells signaling in cardiomyocytes and leads to cardiac hypertrophy and myocardial fibrosis in rodents." (PMID 38124483, 2024). "FGF23 induces hypertrophic growth of cultured cardiac myocytes via FGFR4, and deletion or blockade of FGFR4 in CKD rodent models with elevated FGF23 protects from cardiac hypertrophy." (PMID 39452290, 2024). "A major limitation of this work is the lack of data on fibroblast growth factor 23 and other important endpoints, including cardiac hypertrophy." (PMID 38344732, 2024). "Moreover, crosstalk between FGF23 and RAAS results in the induction of cardiac hypertrophy and fibrosis." (PMID 36909314, 2023). "Experimental studies have shown that FGF23 activates fibroblast growth factor receptor 4 (FGFR4)/phospholipase Cγ/calcineurin/nuclear factor of activated T-cells signaling in cardiomyocytes and induces cardiac hypertrophy in rodents." (PMID 36909314, 2023). "Moreover, the HW/BW ratio was also significantly higher in CH group rats than controls (p < 0.05), as were serum concentrations of the cardiac hypertrophy markers NT-pro BNP and FGF-23 (both p < 0.001)." (PMID 36030321, 2022).